OPTN (optineurin)
Description:
Plays an important role in the maintenance of the Golgi complex, in membrane trafficking, in exocytosis, through its interaction with myosin VI and Rab8. Links myosin VI to the Golgi complex and plays an important role in Golgi ribbon formation. Plays a role in the activation of innate immune response during viral infection. Mechanistically, recruits TBK1 at the Golgi apparatus, promoting its trans-phosphorylation after RLR or TLR3 stimulation. In turn, activated TBK1 phosphorylates its downstream partner IRF3 to produce IFN-beta/IFNB1. Plays a neuroprotective role in the eye and optic nerve. May act by regulating membrane trafficking and cellular morphogenesis via a complex that contains Rab8 and huntingtin (HD). Mediates the interaction of Rab8 with the probable GTPase-activating protein TBC1D17 during Rab8-mediated endocytic trafficking, such as that of transferrin receptor (TFRC/TfR); regulates Rab8 recruitment to tubules emanating from the endocytic recycling compartment. Autophagy receptor that interacts directly with both the cargo to become degraded and an autophagy modifier of the MAP1 LC3 family; targets ubiquitin-coated bacteria (xenophagy), such as cytoplasmic Salmonella enterica, and appears to function in the same pathway as SQSTM1 and CALCOCO2/NDP52. (Microbial infection) May constitute a cellular target for various viruses, such as adenovirus E3 14.7 or Bluetongue virus, to inhibit innate immune response. During RNA virus infection, such as that of Sendai virus, negatively regulates the induction of IFNB1.
Synonyms: FIP-2; TFIIIA-IntP; FIP2; GLC1E; HIP7; HYPL; NRP; ALS12
Tractability: Small molecule: a structure with a bound ligand is known. PROTAC: ubiquitination databases record sites on it; its protein half-life has been measured.
Gene: Protein-coding gene on chromosome 10 (13,099,449 to 13,140,320, forward strand). Ensembl gene ENSG00000123240.
Subcellular location: Cytoplasm, perinuclear region; Golgi apparatus; Golgi apparatus, trans-Golgi network; Cytoplasmic vesicle, autophagosome; Cytoplasmic vesicle; Recycling endosome
Subcellular location (Human Protein Atlas): Cytosol
Pathways (Reactome):
Immune System: Activation of IRF3, IRF7 mediated by TBK1, IKKε (IKBKE); Regulation of TBK1, IKKε (IKBKE)-mediated activation of IRF3, IRF7; Regulation of TBK1, IKKε-mediated activation of IRF3, IRF7 upon TLR3 ligation; TICAM1-dependent activation of IRF3/IRF7
Signal Transduction: Regulation of TNFR1 signaling; TNFR1-induced NF-kappa-B signaling pathway; TNFR1-induced proapoptotic signaling
Autophagy: PINK1-PRKN Mediated Mitophagy
Cell Cycle: Regulation of PLK1 Activity at G2/M Transition
Vesicle-mediated transport: TBC/RABGAPs
Gene Ontology:
Molecular function: identical protein binding; polyubiquitin modification-dependent protein binding; protein binding; protein-macromolecule adaptor activity; K63-linked polyubiquitin modification-dependent protein binding
Biological process: cellular response to unfolded protein; defense response to Gram-negative bacterium; Golgi organization; Golgi ribbon formation; Golgi to plasma membrane protein transport; negative regulation of receptor recycling; positive regulation of autophagy; positive regulation of xenophagy; protein localization to Golgi apparatus; type 2 mitophagy; cell death; regulation of canonical NF-kappaB signal transduction; signal transduction
Cellular component: cytosol; Golgi apparatus; recycling endosome; trans-Golgi network; cytoplasm; Golgi membrane; nucleoplasm; nucleus; recycling endosome membrane; autophagosome; cytoplasmic vesicle; perinuclear region of cytoplasm
Genetic constraint (gnomAD): Loss-of-function variants: 41 observed, 60.65 expected, observed/expected ratio (o/e) 0.68, 90% interval 0.53 to 0.88. The upper end of that interval is the gene's LOEUF score, 0.88, which puts it in group 3 of 6, group 1 being the genes least tolerant of losing a copy. Missense variants: 567 observed, 652.41 expected, observed/expected ratio (o/e) 0.87, 90% interval 0.81 to 0.93. Synonymous variants: 233 observed, 242.88 expected, observed/expected ratio (o/e) 0.96, 90% interval 0.86 to 1.07.
Gene-disease validity (ClinGen):
ClinGen rates the evidence that OPTN causes each of these diseases.
amyotrophic lateral sclerosis type 12 (semidominant): Definitive.
Homologues: Orthologues: chimpanzee OPTN (99% identical), macaque OPTN (96% identical), dog OPTN (85% identical), pig OPTN (84% identical), rat Optn (81% identical), guinea pig OPTN (81% identical), mouse Optn (79% identical), rabbit OPTN (75% identical), tropical clawed frog optn (42% identical), zebrafish optn (38% identical). Paralogues in human: IKBKG (21% identical).
Diseases named in the same sentence as OPTN in open-access papers:
OPTN is named in the same sentence as 139 diseases in open-access papers, as found by Europe PMC text mining. Sharing a sentence is not in itself a finding about the gene and the disease. The quoted sentences say what the papers report.
glaucoma (177 papers, 2007 to 2026). Increased pressure in the eyeball due to obstruction of the outflow of aqueous humor. "Mammalian OPTN (optineurin) has been shown as a SAR (selective autophagy receptor) for ub-dependent mitophagy in vitro with direct connections of its mutations with glaucoma and ALS." (PMID 41799850, 2026). "3D reconstruction of axonal mitochondria, OPTN and LC3b in optic nerves shows that glaucoma-associated OPTN mutations increase the amounts of mitochondria, OPTN, and mito-OPTN outside of the LC3b-labeled axons." (PMID 40795095, 2025). "Although mutations in the OPTN (optineurin) gene were originally found to cause a specific type of glaucoma, they were later identified as a rare cause of both FTD as well as ALS." (PMID 40395983, 2025). "Several genetic risk factors for glaucoma have been identified, including mutations in the Optineurin (OPTN) gene, which encodes a ubiquitin-binding protein OPTN." (PMID 39448868, 2025). "The glaucoma-associated OPTN mutations not only had the largest fraction of stopped OPTN and LC3b within axons, but also led to large amounts of OPTN being found outside of the axons, some of which reached the surface of the optic nerve." (PMID 40795095, 2025). "The OPTN Glu50Lys (OPTN-E50K; rs28939688) missense mutation is linked with autosomal dominant forms of the disease, and patients harboring OPTN-E50K mutations are predisposed to severe forms of glaucoma and have poor prognoses." (PMID 39448868, 2025). "Our studies demonstrate that expression of OPTN carrying a glaucoma-associated mutation results in increased transcellular degradation of axonal mitochondria." (PMID 40795095, 2025). "Mutations in OPTN are linked with several human pathologies including glaucoma, Paget’s disease of bone, Crohn’s disease, and neurodegenerative diseases such as amyotrophic lateral sclerosis, and dementia." (PMID 41294799, 2025). "The glaucoma-associated E50K OPTN also significantly increased the fraction of mitochondria co-localizing with OPTN, and this increased co-localization was observed not only in the stationary but also the two moving populations." (PMID 40795095, 2025). "(B) Percentage of OPTN outside LC3b-labeled RGC axons is significantly higher or trends so in the glaucoma-associated OPTN mutations." (PMID 40795095, 2025). "Mutations in the autophagy gene Optineurin (OPTN) are associated with primary open-angle glaucoma (POAG), amyotrophic lateral sclerosis (ALS), and Paget’s disease of the bone, but the pathophysiological mechanism is unclear." (PMID 39302926, 2024). "Recent studies have reported that the missense variant p.E50K is the only known variant in the OPTN gene associated with glaucoma, whereas loss-of-function variants in this gene are associated with amyotrophic lateral sclerosis (ALS)." (PMID 38241218, 2024). "Mutations in autophagy gene Optineurin (OPTN) are associated with primary open-angle glaucoma (POAG), amyotrophic lateral sclerosis (ALS), Paget’s disease of the bone, but the pathophysiological mechanism is unclear." (PMID 39302926, 2024). "Pathogenic variants in TBK1, MYOC, and OPTN are associated with primary open-angle glaucoma (POAG) with severe visual field defects." (PMID 39669598, 2024). "The phenotype of affected individuals with OPTN variants is notable for glaucoma associated with normal intraocular pressure (IOP), commonly referred to as normal tension glaucoma (NTG), in a large proportion of affected family members." (PMID 39456800, 2024). "Optineurin (OPTN) is a causative gene of several human diseases, including primary open-angle glaucoma, Paget’s disease of bone, Crohn’s disease, and amyotrophic lateral sclerosis (ALS)." (PMID 37352136, 2023). "In an earlier section, we described a publication that reported on the amino acid sequences of the glaucoma-associated genes myocilin and optineurin." (PMID 37760829, 2023).
glaucoma (continued). "Optineurin (OPTN) was initially reported as a causative gene for glaucoma and was later found to contribute to ALS pathology." (PMID 37566027, 2023). "Remarkably, BX795 treatment not only reduced cellular apoptosis at the basal level but also under CCCP-induced apoptosis in the E50K hRGCs, making it a strong candidate for OPTN mutation-associated glaucoma neuroprotection therapy." (PMID 36828933, 2023). "The introduction of the E50K mutation in optineurin (OPTN) by CRISPR-Cas9 has also been used to model glaucoma in ESC-derived retinal organoids." (PMID 37626665, 2023). "The three Mendelian genes, myocilin, TANK-binding kinase 1 (TBK1) and optineurin (OPTN), have been linked to glaucoma, with the last two genes being mitophagy-related genes." (PMID 37566048, 2023). "OPTN, the most recently identified autophagy receptor, was initially named because it corresponds to one of the genes encoding the glaucoma form of the “optic neuropathy inducing” protein." (PMID 35165261, 2022). "Optineurin (OPTN) is a gene linked to glaucoma, and its encoded protein is an autophagy receptor, which targets specific cargo for degradation and is itself degraded by autophagy." (PMID 36589756, 2022). "Another glaucoma-associated mutation of OPTN, 691_692insAG (or 2bpIns-OPTN), was shown to increase ER stress and upregulate CHOP expression resulting in cell death." (PMID 35346303, 2022). "Optic nerve damage, high pressure in the eye causing pain and sudden visual disturbance; when derived from three-dimensional retinal organoids, retinal ganglion cells with a glaucoma OPTN gene mutation exhibit neurodegenerative phenotypes." (PMID 36359825, 2022). "OPTN, earlier reported as causative of primary open-angle glaucoma, was afterwards linked to ALS, or to FTD, with dominant or recessive transmission." (PMID 36570531, 2022). "Glaucoma, caused by an E50K mutation in the optineurin (OPTN) gene, destroys the RGCs that act as a link between the eye and the brain." (PMID 36359825, 2022). "OPTN has been implicated genetically in many human diseases, such as glaucoma, Paget’s disease and amyotrophic lateral sclerosis (ALS)." (PMID 35165261, 2022). "Because OPTN is also genetically associated with other degenerative diseases, such as glaucoma and amyotrophic lateral sclerosis (ALS), our study will potentially offer broader insights into the pathophysiology and treatment of various degenerative conditions." (PMID 33864025, 2021). "Mutations in optineurin (OPTN) associated with primary open angle glaucoma (E50K) reduced the phosphorylation of IRF3 and IFNα/β release assays in response to poly (I:C) stimulation of TLR3." (PMID 34366851, 2021). "Dysfunction in OPTN is implicated in glaucoma and neurodegenerative diseases including ALS and AD5,18." (PMID 34518549, 2021). "The process of mitophagy is PINK1/Parkin mediated and requires recruitment of autophagy receptors like optineurin (OPTN) and mutations in gene OPTN are first described in patients with glaucoma and later in ALS patients." (PMID 34575995, 2021). "The introduction of the E50K mutation in the optineurin (OPTN) gene enabled the modeling of glaucoma in retinal organoids and the knockout of RB1 demonstrated its crucial role in retinal development." (PMID 33800815, 2021). "In conclusion, our results showed that the glaucoma-associated E50K OPTN mutation induced RGC reduction and visual impairment in vivo and cell apoptosis in vitro." (PMID 33723228, 2021). "TBK1 is the binding partner of optineurin, an established glaucoma gene, and copy number variants in TBK1 have been associated with normal tension glaucoma (NTG) most commonly as well as primary open-angle glaucoma (POAG)." (PMID 34258050, 2021). "Given the wide variety of cell functions regulated by Rab8 and OPTN, however, there is still some uncertainty of how OPTN glaucoma-causing mutants function to cause RGC death." (PMID 34201955, 2021).
glaucoma (continued). "Studies with the glaucoma-associated OPTN H486R mutant demonstrated loss of interaction of OPTN and CYLD, which resulted in increased NF-κB signaling induced by inflammatory cytokines." (PMID 33953963, 2021). "Some OPTN mutations are correlated with POAG pathogenesis, whereas glaucoma-associated OPTN mutations constitute mostly missense mutations." (PMID 32545285, 2020). "Among genes implicated in glaucoma, either by GWAS or as rare Mendelian alleles, most were expressed predominantly within RGCs (e.g., OPTN, TMCO1, TBK1)." (PMID 32555229, 2020). "Glaucoma-associated missense mutations of OPTN include, among others, E50K, H26D, H486R, and E322K, whereas E50K constitutes the most common OPTN mutation and is strictly associated with the more severe form of glaucoma." (PMID 32545285, 2020). "Optineurin (OPTN), an autophagy receptor causative for glaucoma and ALS, is recruited to the mitochondrial surface where it interacts with ubiquitin through its ubiquitin binding in ABIN and NEMO (UBAN) domain." (PMID 31934852, 2020). "An increasing number of perturbations in OPTN gene function have been linked to diseases including primary open-angle glaucoma (POAG), amyotrophic lateral sclerosis (ALS), Paget's disease of bone (PDB) and Crohn's disease (CD)." (PMID 32376785, 2020). "The clinical relevance of OPTN has been indicated by the genetic variants/mutations of OPTN linked to glaucoma, Paget’s disease of bone and amyotrophic lateral sclerosis." (PMID 30669622, 2019). "Defects in autophagy pathways caused by mutations in OPTN have been associated with human disorders like glaucoma, Paget disease of bone, and amyotrophic lateral sclerosis." (PMID 30818338, 2019). "Although NTF deprivation is not considered as the primary cause of glaucoma, evidence for a linkage between NTFs and two of the most prevalent glaucoma risk genes—myocilin and optineurin—has been found." (PMID 31484425, 2019). "OPTN is an autophagy cargo adapter protein genetically linked to amyotrophic lateral sclerosis and glaucoma." (PMID 29867311, 2018). "OPTN has been implicated in a variety of human diseases including glaucoma, amyotrophic lateral sclerosis, Paget’s disease, and recently, inflammatory bowel disease (IBD)." (PMID 29692785, 2018). "Approximately 10% of glaucoma cases are the result of genetic variants of myocilin, optineurin or WDR36, and 20% of primary open-angle glaucoma patients are involved in an even wider genetic link." (PMID 30371760, 2018). "Glaucoma-associated mutations of OPTN are mostly missense mutations, whereas ALS-associated mutations include deletions, missense, and nonsense mutations." (PMID 29951055, 2018). "One of the genes mutated in ALS, as well as in glaucoma, encodes optineurin, a ubiquitously expressed protein involved in neuroinflammation, Golgi maintenance, vesicular trafficking, and autophagy." (PMID 29875767, 2018). "Glaucoma-associated mutants of OPTN, E50K, and M98K, cause defective vesicle trafficking, autophagy, and signaling that contribute to death of retinal ganglion cells (RGCs)." (PMID 29951055, 2018). "This is perhaps the only mutation of OPTN known so far that is associated with glaucoma as well as ALS." (PMID 29951055, 2018). "Certain mutations in OPTN are associated with glaucoma, an eye disease that causes progressive irreversible blindness." (PMID 29951055, 2018). "A cytoprotective function of OPTN was proposed to explain pathogenesis of glaucoma, which is impaired by mutations." (PMID 29951055, 2018). "The altered interactions of glaucoma-associated OPTN mutants with proteins involved in immune response and/or NF-κB signaling raises the possibility of involvement of autoimmunity in glaucoma pathogenesis by these mutants, which is yet to be explored." (PMID 29951055, 2018). "Since OPTN has a role in immune signaling pathways, the involvement of OPTN and its mutants in autoimmunity associated with glaucoma needs to be explored." (PMID 29951055, 2018).